TMED7 (transmembrane p24 trafficking protein 7)
Description:
Potential role in vesicular protein trafficking, mainly in the early secretory pathway. Appears to play a role in the biosynthesis of secreted cargo including processing and post-translational modifications.
Synonyms: p24gamma3; CGI-109; FLJ90481; p24g3; Tag; p27
Tractability: Antibody: UniProt predicts a signal peptide or a membrane-spanning region. PROTAC: ubiquitination databases record sites on it; its protein half-life has been measured.
Gene: Protein-coding gene on chromosome 5 (115,613,210 to 115,634,830, reverse strand). Ensembl gene ENSG00000134970.
Subcellular location: Endoplasmic reticulum membrane; Golgi apparatus, cis-Golgi network membrane; Endoplasmic reticulum-Golgi intermediate compartment membrane; Cytoplasmic vesicle, COPI-coated vesicle membrane; Cytoplasmic vesicle, COPII-coated vesicle membrane
Pathways (Reactome):
Vesicle-mediated transport: COPI-dependent Golgi-to-ER retrograde traffic; COPI-mediated anterograde transport
Gene Ontology:
Molecular function: protein binding
Biological process: endoplasmic reticulum to Golgi vesicle-mediated transport; Golgi organization
Cellular component: endoplasmic reticulum; endoplasmic reticulum-Golgi intermediate compartment; Golgi apparatus; COPI vesicle coat; COPII vesicle coat; endoplasmic reticulum membrane; endoplasmic reticulum-Golgi intermediate compartment membrane; Golgi membrane; transport vesicle; COPI-coated vesicle membrane; ER to Golgi transport vesicle membrane
Genetic constraint (gnomAD): Loss-of-function variants: 8 observed, 21.61 expected, observed/expected ratio (o/e) 0.37, 90% interval 0.22 to 0.67. The upper end of that interval is the gene's LOEUF score, 0.67, which puts it in group 2 of 6, group 1 being the genes least tolerant of losing a copy. Missense variants: 232 observed, 273.01 expected, observed/expected ratio (o/e) 0.85, 90% interval 0.76 to 0.95. Synonymous variants: 121 observed, 105.28 expected, observed/expected ratio (o/e) 1.15, 90% interval 0.99 to 1.34.
Homologues: Orthologues: chimpanzee TMED7 (100% identical), dog TMED7 (98% identical), mouse Tmed7 (96% identical), guinea pig TMED7 (95% identical), rabbit TMED7 (95% identical), macaque TICAM2 (85% identical), pig TMED7 (83% identical), tropical clawed frog tmed7 (80% identical), zebrafish tmed7 (76% identical), Caenorhabditis elegans tmed-3 (50% identical), Drosophila melanogaster p24-1 (42% identical). Paralogues in human: TMED3 (62% identical), TMED1 (33% identical), TMED2 (31% identical), TMED5 (30% identical), TMED4 (27% identical), TMED9 (26% identical), TMED6 (20% identical), TMED10 (18% identical).
Diseases named in the same sentence as TMED7 in open-access papers:
TMED7 is named in the same sentence as 11 diseases in open-access papers, as found by Europe PMC text mining. Sharing a sentence is not in itself a finding about the gene and the disease. The quoted sentences say what the papers report.
nasopharyngeal carcinoma (2 papers, 2015 to 2023). A carcinoma arising from the nasopharyngeal epithelium. "For the UC Bead GRN, RNF17 (TDRD4) is a potential liver cancer CT antigen and TMED7 was observed to be upregulated in a nasopharyngeal carcinoma cell line and described to act as a major immune system switch." (PMID 25971253, 2015).
colorectal cancer (1 paper, 2023). A primary or metastatic malignant neoplasm that affects the colon or rectum. "Also, while neither TMED7 (transmembrane p24 trafficking protein 7) nor FUCA2 (alpha-L-fucosidase 2) genes are known to be linked to colorectal cancer, FUCA2 is associated with various cancers, tumor microenvironment and prognostic features." (PMID 36998434, 2023).
dysferlinopathy (1 paper, 2023). "Comparative analysis between PM and dysferlinopathy revealed that the DEGs upregulated in PM were most abundant in the protein localization to organelle pathway and helped identify four genes (KDELR3, C0PB2, TMED7, and RAB1A) that were related to ER to Golgi vesicle–mediated transport." (PMID 38125829, 2023).
iron-overload (1 paper, 2018). "Of these only 3 genes (CD163, ADAM17, and TMED7) were significantly linked to systemic iron-overload based on multivariate projection model analyses." (PMID 29980709, 2018).
joint disease (1 paper, 2023). "Although none have been described in joints or OA, CD81, calumenin, and TMED7 are promising candidates for further studies, focusing in particular on their potential ability to influence inflammation and degradation processes, to better understand their role in joint disease." (PMID 37443777, 2023).
tumor (3 papers, 2018 to 2023). "These included genes with homologs involved in tumor suppression (OPCML), cell growth regulation (CDKL3), DNA repair (FANCL), and innate immunity (TMED7-TICAM2)." (PMID 30845962, 2019).
cancer (2 papers, 2019 to 2023). A tumor composed of atypical neoplastic, often pleomorphic cells that invade other tissues. "Little is known about the TMED family in cancer and, specifically, nothing is known about the possible participation of TMED9 and TMED7 in metastases." (PMID 31253868, 2019).
neurodegenerative disease (1 paper, 2022). A disorder of the central nervous system characterized by gradual and progressive loss of neural tissue and neurologic function. "This is interesting since both TMED7 and Arl1 are involved in Golgi vesicle-mediated transport, and its alteration is likely to induce Golgi fragmentation in neurodegenerative diseases, including AD and PD." (PMID 35563596, 2022).
TMED7 also shares sentences with these, for which no sentence is quoted: breast carcinoma (1 paper); liver cancer (1); pneumonia (1).